LAMC2 (laminin subunit gamma 2)
Diseases named in the same sentence as LAMC2 in open-access papers (continued):
Sharing a sentence is not in itself a finding about the gene and the disease.
tumor (continued). "Of note, LAMC2 has been previously identified as a specific marker for tumor budding in multiple tumor types, including CRC18, and we confirmed that its expression correlated with EMP1 mRNA in CRC patient samples." (PMID 36352230, 2022). "To assess the capacity of these tumor cell populations to serially propagate the disease into secondary hosts, we inoculated 200 or 1,000 LAMC2-EGFP+ or EGFP− epithelial tumor cells into new recipient mice." (PMID 36289544, 2022). "We report a LAMC2-expressing cell population, which is endowed with enhanced self-renewal capacity, and is sufficient for tumor initiation and differentiation, and drives metastasis." (PMID 36289544, 2022). "The results showed that the expression of LAMC2 was significantly increased in tumor tissues compared with the normal tissues." (PMID 36284634, 2022). "A substantial proportion of the epithelial compartment of the tumor showed LAMC2-EGFP+ cells, with their EGFP levels varying considerably." (PMID 36289544, 2022). "The effect of knockdown of LAMC2 on the expression of LAMC2, Ki-67, E-cadherin, and integrinβ1 was investigated by western blot in tumor tissues of nude mice." (PMID 36284634, 2022). "LAMC2 mRNA levels were consistently and significantly higher in tumor tissue versus adjacent normal tissue." (PMID 36289544, 2022). "In PDAC, the elevated expression of LAMC2 has been detected not only in tumor tissues but also in serum." (PMID 36612197, 2022). "High expression of LAMC2 promotes tumor metastasis via the epithelial–mesenchymal transition and epidermal growth factor receptor pathways." (PMID 35506252, 2022). "Seven ECMGs (i.e. LAMB3, LAMA3, ITGB6, ITGB4, ITGA2, LAMC2, and COL11A1) were identified to be hub genes of PAAD, which were obviously up-regulated in PAAD and considerably linked to tumor stage as well as prognosis." (PMID 36311789, 2022). "Intriguingly, targeting the tumor bulk cells as well as LAMC2-high TICs with Vactosertib, a new specific inhibitor of the TGF-β receptor type 1 (TGFBR1), efficiently inhibited PDAC progression and abrogated metastasis." (PMID 36289544, 2022). "Most of the extracellular spaces of the tumor areas showed accumulation of LAMC2 and expression of LAMC2 at tumor stroma interfaces indicates invasion and cancer progression." (PMID 33420101, 2021). "We then found that the expression of LAMC2 was elevated in PC tumor tissues through the GEO database, IHC and WB analysis." (PMID 34606473, 2021). "In a second validation study, we explored the expression of RUNX2 and LAMC2 in different clinical stage, sex, age, tumor subtype and personal tumor status groups." (PMID 34606473, 2021). "Uploading the upregulated genes to STRING for GO enrichment, the results showed that CCL11, LAMC2, and MMP9 were associated with cell migration and cell proliferation, which are closely related to tumor progression." (PMID 34612783, 2021). "Early studies have reported that LAMC2 exists in the tumor microenvironments and influences the invasion and migration of cancer cells 17, 18.The tumor microenvironment plays a critical role in influencing the biological behavior of cancer cells." (PMID 33995623, 2021). "We also identified LAMC2 with significantly related expression to GPR115 that promotes tumor metastasis for LUAD." (PMID 33330053, 2020). "Laminin subunit gamma 2 (LAMC2) is expressed in tumor cells and can be used as a marker of malignant epithelial cells." (PMID 32467737, 2020). "Among these, COL17A1, ITGB6, LAMC2, and S100P were upregulated in tumor tissues, whereas only CHGA was downregulated." (PMID 33015155, 2020). "LAMC2 is an epithelial-specific basement membrane protein that plays an important role in promoting tumor EMT." (PMID 33330053, 2020). "The violin plot showed the metastasis-related genes were higher expression in LUAD tumor tissues, but only LAMC2, THBS2, ITGB4, COL1A1 and FLNC showed positively correlated with poorer survival of LUAD and the expression level of GPR115." (PMID 33330053, 2020).
tumor (continued). "The cytoplasmic expression of LAMC2 represents the high invasive potential of the tumor and is correlated with distant metastasis, especially hepatic metastasis, and with a poorer prognosis in patients with PDAC." (PMID 31182680, 2019). "The results show that LAMA3 and LAMC2 expression is significantly upregulated in PDAC tumor tissues in most studies." (PMID 31182680, 2019). "Two key differentially expressed subunits (LAMA3 and LAMC2) that are associated with prognosis of PDAC patients were found to show a potential for distinguishing between PDAC and non-tumor tissues." (PMID 31182680, 2019). "Next, the RT-qPCR results indicated that LAMC2 was overexpressed in 89.4% (59/66) of ESCC tissues, and high LAMC2 expression was associated with primary tumor invasion depth, lymph node metastasis, and advanced TNM stage." (PMID 29511340, 2018). "In analogy to the published intratumoral localization of pEMT-signature genes LAMB3 and LAMC2, pERK1/2 and especially Slug were frequently expressed in cells of the leading edge of tumor areas in our cohort." (PMID 30261040, 2018). "Knockdown of LAMC2 (or rescue of miR-622) expression or knockdown of miR-197 (or rescue of CD82) expression in MGC-803 cells inhibited tumor cell invasion." (PMID 28252644, 2017). "The elevated expression of LAMC2 in tumour cells appears to drive tumourigenesis through its interactions with several cell‐surface receptors including α6β4 and α3β1 integrins and epidermal growth factor receptors." (PMID 27704726, 2017). "MiR-29 family has also demonstrated its tumor suppressor role by targeting laminin γ2 (LAMC2) and α6 integrin (ITGA6) resulting in the inhibition of cell migration and invasion in HNSCC cell line (SAS and FaDu)." (PMID 27391030, 2016). "In this study, we used immunohistochemistry to study the expression of a panel of transcription factors (TWIST1, SNAI1/2, ZEB1 and ZEB2) and other genes intimately related to EMT (CDH1 and LAMC2) at the invasive tumor front of OSCC tissues." (PMID 26214683, 2015). "Most notably, LAMC2, the γ2 chain of Laminin 332, has been shown to be involved in tumor migration and invasion processes." (PMID 26214683, 2015). "The expression level of miR-218 was significantly downregulated in tumor tissues compared with adjacent normal tissues (p = 0.039), whereas LAMA3, LAMB3 and LAMC2 were upregulated in tumor tissues (P = 0.018, p = 0.0029 and p = 0.0009, respectively)." (PMID 23159910, 2012). "Next, transcription factor analysis using the SCENIC pipeline revealed that HMGA2, a key transcription factor known to regulate LAMC2 expression in tumors, was significantly activated in Tum_1 cells, suggesting a role in promoting tumor basal stem‐like cell activity." (PMID 40470730, 2025). "Additionally, hypoxia drives histone lactylation at H3K9, which in turn enhances the transcription of laminin subunit gamma 2 (LAMC2), contributing to tumor progression by promoting cell adhesion and invasion." (PMID 41373440, 2025). "Notably, the Tum_1 subtype showed elevated expression of LAMC2, which facilitated tumor invasiveness through its interaction with ITGA6/ITGB4." (PMID 40470730, 2025). "Functionally, silencing LAMC2 significantly blocks tumor formation in orthotopic iCCA mouse models." (PMID 38526177, 2024). "Taken together, these studies reaffirm our bioinformatics-based analysis and suggest that these extracellular matrix genes (CDH3, COL11A1, COL1A1, COL17A1, KRT19, ITGA2, LAMC2, and SULF1) are highly associated with PDAC tumor carcinogenesis and peritoneal metastasis." (PMID 39682235, 2024). "Results from animal experiments confirmed the tumor-promoting capacity of LAMC2 under ER stress." (PMID 37891404, 2024). "In summary, we identified the histone Kla landscape under hypoxia in ESCC and showed that histone H3K9la could activate the LAMC2 transcription to promote the tumor progression." (PMID 38989468, 2024).
tumor (continued). "TCGA data also showed that LAMC2 was significantly increased with multiple tumor tissues." (PMID 38989468, 2024). "In addition, LAMC2 can interact with integrin β1 to promote colorectal cancer tumor budding by activating Yes-related protein." (PMID 37891404, 2024). "Moreover, overexpression of LAMC2 counteracts the effects of ER stress and promotes tumor growth in vivo." (PMID 37891404, 2024). "Considering that LAMB3 and LAMC2 are established prognostic markers in various cancer types, our findings may also have implications for endothelial cells within tumor microenvironment." (PMID 39201392, 2024). "Findings from this study suggested that LAMC2 can serve as a novel target for tumor therapy." (PMID 37891404, 2024). "Interestingly, the Ki-67 protein (MKI67)-expressing proliferative cancer cells were located at the tumor margin between LAMC2- and SPRR3-positive cells, further supporting the proliferative potential to differentiate into various mEpC types." (PMID 37853464, 2023). "Moreover, LAMC2 was highly expressed in tumor tissues compared with normal tissues, exhibiting a significant difference." (PMID 37415741, 2023). "Among the genes positively co-expressed with LAMA3, LAMB3, and LAMC2, there are important proteins which may change cancer cell behaviour and cancer progression in different tumours." (PMID 37779898, 2023). "Interestingly, when LAMC2 was overexpressed by plasmid transfection on tumor cells with high LAMC2 expression, it had a beneficial effect on the biological behavior of OSCC through the PI3K/AKT/mTOR pathway." (PMID 37415741, 2023). "Interestingly, tumor size, weight, and volume were similar between the control + Gefitinib and LAMC2 + Gefitinib groups." (PMID 37542131, 2023). "In addition, we co-transfected A549 and NCI-H23 cells with EGFR overexpressing vector and LAMC2 siRNA to assess their potential counteracting effects on tumor cell activity, proliferation, cell cycle, and apoptosis." (PMID 37542131, 2023). "Patients with the upper third LAMA3 (p = 0.01), LAMB3 (p = 0.01) and LAMC2 (p = 0.01) transcript abundance were each associated with a higher histological grade, while high LAMA3 (p = 0.001) and LAMC2 (p = 0.01) were associated with the residual tumour stage." (PMID 37779898, 2023). "As changes in the laminin gene expression have been associated with changes to the immunophenotype of a tumour in different contexts, we also queried the LAMA3, LAMB3, and LAMC2 genes in the TIMER2.0 database to investigate their relationship with tumour-infiltrating lymphocytes." (PMID 37779898, 2023). "Moreover, tumor clusters had higher expression levels of tumor makers, including LAMC2, MSLN, TFF2, and CEACAM5, compared with ductal clusters, which further verified their tumor identity." (PMID 36944944, 2023). "We found that LAMC2 (laminin subunit gamma 2) showed spatial pattern and was involved in spatial pathways such as ‘cell differentiation’ and ‘metabolic process’ in the tumor region, which was reported previously to promote tumor metastasis." (PMID 36243975, 2023). "Furthermore, SLUG colocalized with EGFR and pEMT marker LAMC2 in selected patients with a homogeneous or a peripheral SLUG expression at the edges of tumor areas." (PMID 34382739, 2022). "Knockdown of LAMC2 inhibited LSCC cell tumor growth in vivo in xenograft experiments." (PMID 36284634, 2022). "Furthermore, we evaluated the possible link between the ECMGs and the tumor stage of PAAD, and 8 ECMGs (i.e. FN1, LAMA3, ITGB6, ITGB4, ITGA2, LAMC2, COL11A1, LAMB3) were detected to be significantly associated with tumor stage." (PMID 36311789, 2022). "In OSCC, LAMC2 functions as an oncogenic factor and promotes tumor cell growth." (PMID 35506252, 2022). "Moreover, the effect of LAMC2 on LSCC tumor growth was evaluated by in vivo xenograft experiments and western blot." (PMID 36284634, 2022). "Strategies aimed at targeting the LAMC2 population may be effective in reducing tumor aggressiveness in PDAC patients." (PMID 36289544, 2022).
tumor (continued). "In addition, a novel mechanism for BBOX1-AS1 function is that it modulates miR-3940-3p/LAMC2 signaling to exert tumor-promoting effects." (PMID 35506252, 2022). "LAMC2, which encodes the laminin subtype LN-332 γ2 chain, is associated with poor prognosis, infiltrating immune cells and higher levels of LAMC2 protein expression, particularly in tumour-budding areas in HNSCC contributing to proliferation, migration, invasion and metastasis." (PMID 35327656, 2022). "Overall, the ROC analysis of the laminins in the OC sets indicated that LAMA2/A4/A5, LAMB1/B2/B3, and LAMC2 could be considered to accurately differentiate between tumor and non-tumor tissues." (PMID 34512203, 2021). "However, LAMC2 were significantly elevated not only in advanced PC patients, but also in the ductal type PC group (P=0.03) and PC patients which with tumor group (P=0.02)." (PMID 34606473, 2021). "The ROC analysis of the laminins in OC datasets showed that the LAMA2/A4/A5, LAMB1/B2/B3, and LAMC2 mRNA levels could be considered to effectively differentiate between malignant tumor and non-tumor tissues." (PMID 34512203, 2021). "In addition, LAMC2, HMGA1 and CSTB were discovered to be upregulated significantly along with trajectory transition and elevated in the metastatic tumor lesions, which was consistent with published researches focusing on biological roles of LAMC2/ HMGA1." (PMID 34732701, 2021). "Furthermore, in the tumor masses arising in TG mice, we detected the downregulation of LAMC2 and MSX1 (laminin subunit gamma 2- and MSH homeobox 1-encoding genes, respectively), which are also downregulated in human poorly differentiated EC24." (PMID 33893331, 2021). "The protein expression of LAMC2 was lower in the tumor tissues compared to the normal tissue." (PMID 32640634, 2020). "And GPR115 might activated tumor malignant progression by correlated with LAMC2 to enhanced EMT development." (PMID 33330053, 2020). "The LAMC2 has an epidermal growth factor (EGF)-like domain which can be processed by MMP to interrupt the hemidesmosomes via EGFR of b4 integrin during tumor cell migration." (PMID 32467737, 2020). "We hypothesize that high expression of LAMC2 promotes PDAC cell invasion of the nerve and leads to an increased risk of tumor recurrence." (PMID 31182680, 2019). "The increased availability of Mmp2 and Mmp12 as well as their substrates Col1a1, Col4a1, Col6a1 and LamC2 could indicate that the tumour cells generated foremost collagens, which can be cleaved by these Mmps." (PMID 30603057, 2018). "On the other hand, the decreased levels of mRNAs encoding type I collagen, type IV collagen, laminin subunit gamma 2 and two proto oncogenes WNT7B and CTHRC1, suggest a complex and profound effect of the sera of patients with spontaneous tumour regression on the cancer cells." (PMID 27704726, 2017). "Furthermore, overexpression of LAMC2 in OSCC is also associated with loss of cell polarity, likely suggesting a role in tumor spread." (PMID 26214683, 2015). "LAMC2 is an established β-catenin target gene and nuclear β-catenin has been reported to correlate with intracellular accumulation of γ2 at invasive margins and in budding tumor cells." (PMID 20307265, 2010). "For example, it is essential to explore whether LAMC2 specifically influences the invasive phenotype of Tum_1 tumor subtype and whether it can synergize with existing therapeutic strategies, such as immune checkpoint inhibitors, to enhance therapeutic outcomes." (PMID 40470730, 2025). "In addition, we identified its spatial gene patterns that are located in the tumor area, which is consistent with previous reports that LAMC2 may promote tumor cell metastasis." (PMID 36243975, 2023). "However, an increased level of autophagy caused by LAMC2 downregulation can use drugs to return the level of autophagy to the baseline level in OSCC, reversing the inhibitory effect of breaking autophagy homeostasis induced by tumor biological behavior." (PMID 37415741, 2023).
tumor (continued). "Finally, knockdown LAMC2 inhibited LSCC cell xenograft tumor growth in vivo." (PMID 36284634, 2022). "In addition, the innovation of this study lied in the collection of clinical information and samples for testing, as well as mouse tumor-bearing experiments to explore the correlation between LAMC2 overexpression and LSCC proliferation, invasion, and prognosis." (PMID 36284634, 2022). "Interestingly, in our cohort, the tumor area facing the stroma had a higher expression of LAMC2." (PMID 33420101, 2021). "Furthermore, the high expression level of LAMC2 could facilitate the invasion of PDAC cell and thus increase the risk of tumor recurrence." (PMID 33178697, 2020). "However, LAMC2 expression was still elevated in PDAC tumor tissues." (PMID 31182680, 2019). "While canonical EMT is well-studied in cancer progression, the hEMT state—marked by co-expression of epithelial (e.g., CDH1, IRF6, JUP) and mesenchymal (LAMC2, ITGB4, TGFA) genes—has emerged as a driver that enhances cellular plasticity and tumor metastasis." (PMID 40777467, 2025). "This subtype exhibited enhanced basal‐like and stemness features and showed high LAMC2 expression, which activated laminin‐integrin signaling via ITGA6/ITGB4, promoting tumor invasiveness." (PMID 40470730, 2025). "Our study identified LAMC2 as a key molecular driver in PSCC, particularly in the Tum_1 spatial subtype, where it mediates tumor progression through laminin‐integrin binding." (PMID 40470730, 2025). "While these functional experiments highlight the importance of LAMC2 in PSCC, further investigations are needed to determine its applicability in different tumor subtypes and clinical contexts." (PMID 40470730, 2025). "Recently, the panel of tumor suppressor miRNAs in the context of OSCC has been expanded to include miR-5580-3p and miR-376c-3p, which target Laminin Subunit Gamma 2 (LAMC2) and Homeobox B7 (HOXB7), respectively." (PMID 41209683, 2025). "LAMC2, for instance, plays a crucial role in cancer cell invasion and metastasis, while SULF1 is involved in multiple signaling pathways critical for tumor progression." (PMID 39850570, 2024). "In order to clarify the relationship between DRP1 and LAMC2/MYH9/MYH10 complexes, the DRP1 inhibitor Mdivi-1 and Mdivi-1+Tun were used to treat tumor cells." (PMID 37891404, 2024). "All five clusters of tumor epithelial cells were indeed observed in AM samples by using marker genes (HLA-B for IR, SFRP1 for BR, KRT13 for ED, ODAM for TD, LAMC2 for TD, and KI67 for CC)." (PMID 38424060, 2024). "Consistently, overexpressed of LAMC2 resulted in a significant increase in the formation and lung metastasis of ESCC tumor in vivo." (PMID 38989468, 2024). "Meanwhile, overexpressed of LAMC2 increased the level of VEGFA and p-AKT in xenograft tumor tissues." (PMID 38989468, 2024). "The decrease in LAMC2 and LOXL2 secretion correlated with other phenotypic changes, including decreased clonogenicity, tumor sphere formation, spheroid growth, growth in vivo and increased drug sensitivity." (PMID 39496753, 2024). "Among them, six lncRNAs (LASTR, lnc-LAMC2, lnc-ZNF33B, PVT1, MIR205HG, and ENTPD1-AS1) were previously reported to play critical roles in the tumor recurrence and metastasis." (PMID 36894542, 2023). "Lastly, IHC analyses of tumor tissues indicated that Gefitinib effectively reduced Phospho-EGFR and Ki67 protein levels in both control and LAMC2 groups." (PMID 37542131, 2023). "The largest expression differences between tumour and normal samples were observed for LAMA3 (mean fold change; mfc = 21.7, p = 2.1 × 10−61), LAMB3 (mfc = 55.3, p = 7.9 × 10−60), and LAMC2 (mfc = 51.0, p = 3.8 × 10−61) transcripts." (PMID 37779898, 2023). "Lastly, IHC results of tumor tissues corroborated the relative protein expression levels of LAMC2 and EGFR in the three experimental groups in that LAMC2 and EGFR protein levels were highest in the NC group and lowest in the LAMC2 KD group." (PMID 37542131, 2023).